MALAT1 (metastasis associated lung adenocarcinoma transcript 1)
Diseases named in the same sentence as MALAT1 in open-access papers (continued):
Sharing a sentence is not in itself a finding about the gene and the disease.
tumor (continued). "Following studies have documented that MALAT1 was aberrantly up-regulated in multiple cancerous tissues and conferred proliferative and metastatic phenotypes to tumor cells." (PMID 25613496, 2015). "Previous studies showed that Malat1 is abundantly expressed in many tissues and involves in promoting tumor growth and metastasis by modulating gene expression and target protein activities." (PMID 26335021, 2015). "One of these, the metastasis associated in lung adenocarcinoma transcript 1 (MALAT-1), was suggested to be a novel marker for PCa diagnosis: high expression of MALAT-1 correlated with high Gleason score, PSA, tumor stage, and castration-resistant PCa (CRPC)." (PMID 25250334, 2014). "Nonetheless, by regulating SR protein activity, MALAT1 has the potential to actively promote tumor dissemination by modifying the splicing patterns of metastasis-related transcripts." (PMID 24346158, 2014). "Antisense oligonucleotides (ASO) that block MALAT1 prevented metastasis formation after tumor implantation." (PMID 24757675, 2014). "Overexpression of MALAT1 has been shown in various tumours, such as breast, prostate, colon and liver, as well as NSCLC, especially in early-stage metastasizing patients." (PMID 25297942, 2014). "The knockout of MALAT1 resulted in a significant decrease in clonogenicity and colony size, thereby suggesting an important function of MALAT1 in sustaining the transformed phenotype of the tumor cells." (PMID 23717670, 2013). "Nevertheless, we confirmed that MALAT1 plays an important role in tumor metastasis using an A549 metastasis mouse model." (PMID 23717670, 2013). "Previous studies have shown that transient overexpression of MALAT1 enhanced cellular proliferation in cell lines and tumor formation in nude mice, while depletion of MALAT1 in tumor cells reduced tumorigenicity." (PMID 23555285, 2013). "Antisense oligonucleotides (ASO), blocking MALAT1, prevent metastasis formation after tumor implantation." (PMID 23965974, 2013). "The third class of isolated yeast cell death suppressors includes molecules such as PAICS, STEAP1 and MALAT1, for which overexpression and/or functional relevance in tumor biology has been published." (PMID 23717670, 2013). "Importantly, MALAT1 was highly expressed not only in Healthy regions but also in Tumor edge regions, reinforcing our conjecture." (PMID 41490241, 2026). "M2 macrophage-derived exosomal metastasis-associated lung adenocarcinoma transcript 1 (MALAT1) promotes GC progression by activating β-catenin and HIF-1α signaling to enhance glycolysis, while MALAT1 silencing suppresses tumor growth and improves chemosensitivity." (PMID 41171531, 2026). "MALAT1 expression in the tumor was nearly 18 times higher compared to muscle tissue." (PMID 40597438, 2025). "The high expression of MALAT1 was confirmed in tumor cell lines." (PMID 40597438, 2025). "Moreover, lncRNAs such as H19 and MALAT1 have been implicated in resistance to anti-VEGF therapies, facilitating angiogenesis and tumor microenvironment remodeling." (PMID 40781643, 2025). "This downregulation suggests that MALAT1 may act as a tumor suppressor or a prognostic biomarker for Wilms tumor." (PMID 40722750, 2025). "Long non-coding RNAs (lncRNAs), such as NEAT1 and MALAT1, influence immune cell differentiation and tumor progression pathways, providing opportunities for targeted interventions that enhance vaccine-induced immunity while suppressing tumor immune evasion mechanisms." (PMID 40507360, 2025). "Notably, overexpression of MAP2K1 counteracted the anti-tumor effects induced by MALAT1 suppression in HSCC, promoting FaDu cell proliferation and invasion while diminishing apoptosis and hindering cell cycle arrest." (PMID 39319867, 2025). "Similarly, lncRNAs such as HOTAIR and MALAT1 are critical in chromatin remodeling and transcriptional reprogramming, promoting tumor growth and therapy resistance." (PMID 41011238, 2025).
tumor (continued). "Collectively, lncRNA MALAT1 knockdown impeded tumor growth by reducing MAP2K1 expression." (PMID 39319867, 2025). "This confirmed that Cy5.5-MALAT1 ASO specifically binds to MALAT1 in the tumor in vivo." (PMID 40597438, 2025). "Additionally, the knockdown of MALAT1 in HBx-expressing cells suppressed hepatocarcinogenesis phenotypes, and in vivo experiments demonstrated the inhibition of xenograft tumor growth upon MALAT1 knockdown." (PMID 40860202, 2025). "Our study aims to clarify the regulatory axis between miR-423-5p and MALAT-1 and to determine whether miR-423-5p exerts tumor-suppressive effects in HCC by influencing mitochondrial metabolism." (PMID 41029313, 2025). "A functional interaction with the oncogenic lncRNA MALAT-1 has been hypothesized, suggesting a regulatory mechanism that may influence tumor aggressiveness." (PMID 41029313, 2025). "Silencing exosomal MALAT1 significantly inhibits tumor growth in mice and reverses chemoresistance." (PMID 41220952, 2025). "Interestingly, beyond its impact on tumor progression, MALAT1 silencing also affected HBV replication." (PMID 40860202, 2025). "The apparent inverse correlation observed between their expression levels in some cancerous tissues supports the thesis that miR-34a may exert its tumor-suppressive function, at least in part, through MALAT1 downregulation." (PMID 40863726, 2025). "MALAT1 reduces the anti-cancer function of NK cells by decreasing the expression of ligands associated with NK cell activation (e.g., MICA/B) and inducing immune checkpoints (e.g., PD-L1), thereby promoting tumor growth and metastasis." (PMID 40149989, 2025). "Depletion of MALAT1 using ASOs reduced metastasis and tumor burden in mouse models." (PMID 41191214, 2025). "Silencing MALAT1 has been shown to enhance chemosensitivity and suppress tumor growth." (PMID 40781643, 2025). "Additionally, a nude mouse xenograft model was used to confirm the role of lncRNA MALAT1/MAP2K1 in tumor growth." (PMID 39319867, 2025). "Similarly, MALAT1, a long non‐coding RNA, not only regulates gene expression and cellular signaling networks but also enhances tumor cell invasivenes." (PMID 40891683, 2025). "In preclinical models, ASOs targeting MALAT1 effectively reduced its expression, leading to decreased tumor growth and metastasis, suggesting that ASOs could be a viable treatment option for MALAT1-related chemotherapy resistance." (PMID 40781643, 2025). "Additionally, MALAT1 enhances tumor activity by facilitating the dephosphorylation of the ATM protein." (PMID 41141624, 2025). "For instance, it has been reported that inhibiting miR-363-3p or overexpressing EZH2 could partially reverse the anti-tumor effects of MALAT1 depletion, underscoring the functional axis of MALAT1/miR-363-3p/EZH2 in CRC progression." (PMID 40871106, 2025). "lncRNAs such as HOTAIR and MALAT1 affect gene expression through mechanisms like chromatin remodeling and transcriptional interference, which are pivotal in processes such as metastasis and tumor growth." (PMID 40959208, 2025). "MALAT1 is upregulated during KSHV tumor development to promote oncogenesis." (PMID 40733622, 2025). "In addition, increasing data points to the potential of abnormal MALAT-1 expression as a biomarker for tumor diagnosis and prognosis in tumor tissues and/or bodily fluids." (PMID 38511067, 2024). "This outcome implies that MALAT1 inhibition could effectively reduce tumor growth in vivo, highlighting its potential as a therapeutic strategy." (PMID 38791954, 2024). "Consistent with the results of IKE treatment, HBX overexpression also significantly attenuated the inhibitory effect of Erastin on tumor growth, leading to increased tumor volume and weight, while MALAT1 re-expression effectively rescued these inhibitory effects." (PMID 39532842, 2024). "Moreover, LADC had lower MALAT1 mRNA expression levels at large tumor T status (p=0.0116) in all LADC patients." (PMID 38517388, 2024).
tumor (continued). "Targeting MALAT1 significantly reduced tumor sizes in animal models." (PMID 38791954, 2024). "MALAT1 achieves this by modulating multiple molecular pathways involved in DNA repair, apoptosis, and drug efflux, thus diminishing treatment efficacy and contributing to tumor recurrence and progression." (PMID 39015773, 2024). "Next, to further investigate the associations with MALAT1 genotypes for the dominant model (CC versus CT+TT) (rs3200401) in all LADC patients of clinicopathologic characteristics such as tumor stages, tumor T status, lymph node status, distant metastasis and cell differentiation." (PMID 38517388, 2024). "It was observed that the level of MALAT1 varies in tumor tissue compared to normal tissue." (PMID 39725668, 2024). "Similarly, MALAT1’s increased expression augments tumor cell migration and invasion, engaging key signaling pathways like PI3K/AKT/mTOR and Wnt/β-catenin." (PMID 39286016, 2024). "The data indicated that Malat1 drives tumor progression, rather than tumor initiation, consistent with its association with advanced disease and poor prognosis in patients." (PMID 39195572, 2024). "MALAT-1 knockdown decreases sphere formation, colony formation, and tumor size." (PMID 38201661, 2024). "If it is proven that MALAT1 promotes tumor growth, its suppression could also lead to increased permeability of the blood-tumor barrier, allowing for better delivery of anticancer chemotherapy agents." (PMID 39553554, 2024). "Furthermore, one study reports that MALAT-1 sponges the tumor suppressor miR-22 by interacting with zeste homolog 2 (EZH2) enhancers to suppress miR-22 and E-cadherin." (PMID 38201661, 2024). "Furthermore, the xenograft mouse model served as an in vivo validation of the role of MALAT-1 in promoting tumor growth." (PMID 38511067, 2024). "According to the role of MALAT1 in worsening tumor progression, we have shown that WTAP expression levels significantly correlate with the worst clinical outcome shortening the overall survival and disease-free survival, identifying WTAP as a new effector of MALAT1." (PMID 38862471, 2024). "M2‐EX treatment promoted tumor growth in vivo while MALAT1‐depleted M2‐EX had little effect." (PMID 38639382, 2024). "Interestingly, the expression level of MALAT1 is lower in triple-negative breast tumors than in ER+ tumor samples." (PMID 38254873, 2024). "MALAT1 is a known lncRNA regulator of tumor development and is overexpressed in cutaneous SCCs." (PMID 39195246, 2024). "In addition, increased expression level of MALAT1 can also be used as a potential biomarker for tumor diagnosis and prognosis, including liver, colorectal, pancreatic, papillary thyroid, renal cancers and gastrointestinal diffuse large B-cell lymphoma." (PMID 38517388, 2024). "Furthermore, our use of antisense oligonucleotides to inhibit MALAT1 expression led to a significant reduction in tumor sizes in animal models, suggesting the therapeutic potential of targeting lncRNAs." (PMID 38791954, 2024). "These IHC findings suggest that increased MALAT1 expression in AA lung cancer patients may trigger MCP-1 activation, thereby enhancing tumor-associated macrophage presence and altering the tumor microenvironment dynamics." (PMID 38791954, 2024). "Besides, they found a statistically significant correlation between the extent of tumor metastasis and invasion with MALAT1 expression." (PMID 36770654, 2023). "MALAT1, when expressed, promotes the proliferation of tumor cells." (PMID 36969033, 2023). "Meanwhile, the effect of MALAT1 on tumor suppressors in HNSCC should also be explored." (PMID 36813772, 2023). "Besides, MALAT1 is a relatively stable transcript that can be detected in tumor tissue and body fluids with a half-life of 9 to 12 h." (PMID 37667226, 2023). "The data hint that under pro-inflammatory and pro-thrombotic settings (e.g., tumour microenvironment), endogenous or exosomal MALAT1 may promote neutrophil activation, favouring thrombus formation." (PMID 38203310, 2023).
tumor (continued). "Therefore, it is necessary to investigate the mechanism of MALAT1 in chemotherapy resistance to explore new tumor therapeutic targets." (PMID 36829256, 2023). "For example, aberrant expression of MALAT1 was involved in tumor angiogenesis and metastasis." (PMID 37466419, 2023). "In spite of these differences, we also observed that processes as cell proliferation and MAPK pathways were potentially commonly affected by MALAT1 upregulation, and thus could explain its common clinical impact in both neoplasms." (PMID 37803049, 2023). "Furthermore, in vivo MALAT1 suppression reduced PC xenograft tumor growth and metastasis in castrated nude mice." (PMID 36831169, 2023). "Since MALAT1 plays a critical role in tumor development, employing antisense oligonucleotides, small interfering RNA (siRNA), or the CRISPR system might be a promising therapeutic strategy targeting MALAT1." (PMID 37667226, 2023). "As MALAT1 and TUG1 are associated with migration, invasion, metastasis, progression, EMT, relapse-free survival, proliferation, angiogenesis, motility, apoptosis, tumor growth, and tumor size of BC, metformin can regulate these features by MALAT1 and TUG1 activities." (PMID 36849958, 2023). "However, the inclusion of a miR-22-3p inhibitor in the MALAT-1 shRNA-treated tumor cells significantly reversed the inhibitory effect of MALAT-1 shRNA on the expression of p-PI3K and p-Akt." (PMID 38124072, 2023). "Elevated level of MALAT1 results in tumor recurrence in PCa patients." (PMID 37025585, 2023). "Mice were sacrificed at the planned endpoint (day 19) of the experiment, when the average tumor volume in the treatment group remained significantly smaller (−30 %) compared to the control (p = 0.005, MALAT1-ASO: 145 mm3, SD = 28 mm3 vs. Control-ASO: 208 mm3, SD = 7 mm3)." (PMID 37235843, 2023). "Tumor size, tumor stage, and distant metastasis was correlated with MALAT1 high level." (PMID 36793374, 2023). "MALAT1 has been reported to have overexpressed and tumor-promoting functions in NSCLC." (PMID 37667226, 2023). "In contrast, expression of the tumor stem cell marker Cd44 was MALAT1-independent." (PMID 37325561, 2023). "Our results refreshed the understanding of MALAT1 in the autoimmune process, and could also explain the corresponding molecular basis of MALAT1 in tumor immune tolerance escape." (PMID 37873058, 2023). "Zhuang and colleagues revealed that the expression of MALAT1 was directly associated with CRC pathology stage and tumor recurrence, indicating that the high expression of MALAT1 may be used as a marker of advanced CRC and recurrence." (PMID 36797749, 2023). "MALAT1 expression was significantly higher in patients’ OS tissues than in non-tumor tissues." (PMID 36831169, 2023). "For HNSCC, many studies have revealed that MALAT1 could facilitate tumor progression through multiple mechanisms, mainly elevating oncogenic genes expression by serving as a ceRNA to sponge microRNAs." (PMID 36813772, 2023). "When it is an aggravator of tumor-associated angiogenesis, MALAT1 targets the anti-angiogenic miR-150-5p, when it should not be sponged." (PMID 37947637, 2023). "Thus, MALAT1, LUCAT1, and TUG1 are associated with the survival of patients with LC; HOTAIR can serve as a biomarker of tumour progression; and NEAT1 is related to poor prognosis." (PMID 38203731, 2023). "Based on our results, MALAT1 upregulation in BC may function as a tumor promoter in BC via directly sponging miRNA 561-3p, and MALAT1 knockdown serves a vital antitumor role in BC cell progression through the miR-561-3p/TOP2A axis." (PMID 37244966, 2023). "In addition, MALAT1 upregulation correlated with increased Gleason score, tumor progression, and PC castration resistance." (PMID 36831169, 2023). "Thus, MALAT-1 is able to shape an immunosuppressive microenvironment by inhibiting immune effector cells and giving tumor cells the ability to evade immune elimination." (PMID 37637063, 2023).
tumor (continued). "The results of KEGG suggested that the majority of the genes that were significantly associated with the expression of METTL16 and lncRNA MALAT1 were enriched in the Wnt/β-catenin pathway, clarifying that METTL16 possibly plays its tumor suppressive role through inhibiting the Wnt/β-catenin pathway." (PMID 37927399, 2023). "Similarly, MALAT1 affected autophagy of GC cells through a variety of pathways, leading to tumor drug resistance." (PMID 36829256, 2023). "Our findings thus suggest that MALAT1 may play a tumor-promoting role in the development of TNBC tumors." (PMID 37244966, 2023). "One of the most intensively researched possible biomarkers for detecting NSCLC is metastasis-associated lung adenocarcinoma transcript 1(MALAT1), which accelerates tumor migration and proliferation by suppressing cell apoptosis shortening the cell cycle when highly expressed in NSCLC patient serum." (PMID 37641132, 2023). "The results of our study disclosed that MALAT1 could serve as a sponge for miR-561 in BC, and miR-561 is recognized as a tumor suppressor based on previously published research." (PMID 37244966, 2023). "Recently, several studies have shown that the aberrant expression of MALAT1 in tumour tissues may serve as a biomarker for CRC prognosis." (PMID 35558512, 2022). "MALAT1 silencing reduced the tumor volume, while miR-24 had the opposite effect on tumor volume." (PMID 35071748, 2022). "Given the functions of TCF4 and MALAT1 as tumor suppressors, targeting the functional elevation of TCF4 and MALAT1 could be therapeutically beneficial against tumorigenesis." (PMID 36084949, 2022). "Indeed, ASO gapmer‐mediated MALAT1 knockdown was shown to be highly effective in decreasing tumor burden, suppressing metastatic dissemination, and increasing tumor differentiation in xenograft models of metastatic lung and breast adenocarcinomas." (PMID 34668345, 2022). "MALAT1 is highly expressed in a variety of tumor tissues and is involved in tumor regulation." (PMID 35241975, 2022). "Interestingly, in HepG2 cells, MALAT1 was also found in mitochondria, and its knockdown limited ATP synthesis and tumor cell invasion." (PMID 35546353, 2022). "In contrast, MALAT1 was shown to function as a tumor suppressor." (PMID 35954272, 2022). "On the other hand, MALAT1 can function as a tumor suppressor since its expression was found to be positively correlated with the expression of the tumor suppressor PTEN, and their decreased levels were associated with mortality and poor patient survival in both colorectal cancer and BC patients." (PMID 36387279, 2022). "The effect of MALAT1 on tumor cell growth and invasion is controversial." (PMID 36084949, 2022). "Using scRNAseq data from patient samples of primary and recurrent GBM (GSE154975), we identified multiple cell types based on markers from the original study: macrophages (ITGAM), T cells (CD3E), Tregs (CD4, CD3E, FOXP3), low-reads/dying cells (MALAT1), and tumor/normal brain cells (GFAP, SOX2)." (PMID 36591276, 2022). "However, due to the involvement of MALAT1 in multiple processes, its classification as an oncogene or tumor suppressor is under discussion." (PMID 35922756, 2022). "Its function is still controversial that whether it acts as oncogenic or tumor suppressor lncRNA, thus understanding MALAT1 better would be important in epigenetics studies." (PMID 36387279, 2022). "MALAT1 by targeting at least 243 genes stimulates tumor development and enhances CRC cell invasion." (PMID 35305641, 2022). "The lncRNA MALAT1 is a non-coding RNA that commonly occurs in malignant tumor cells." (PMID 36419933, 2022). "MALAT1 sponged miR-124 as this tumor suppressive miRNA was de-repressed upon MALAT1 silencing." (PMID 36059695, 2022). "In this light, therapeutic intervention to reduce MALAT1 intracellular content might restore a physiological metabolism in highly aggressive transformed cells, with resulting detrimental consequences on tumor growth." (PMID 35740569, 2022).